MMP9 (matrix metallopeptidase 9)
Diseases named in the same sentence as MMP9 in open-access papers (continued):
Sharing a sentence is not in itself a finding about the gene and the disease.
metabolic disorders (12 papers, 2014 to 2025). "Thus, dysregulation of MMP-9 can result in metabolic disorders, which could promote the formation of AS." (PMID 31449494, 2019). "MMP-9, TIMP-1, and MMP-9/TIMP-1 ratio correlated with biomarkers of inflammation, kidney and liver injury, coagulation, metabolic disorders, and disease severity scores." (PMID 29861795, 2018). "The importance of understanding the role of MMP-9 and its regulators has previously been emphasized, as it may potentially open up novel therapeutic approaches for treating CVD and metabolic diseases." (PMID 31890043, 2019). "Recent preclinical studies have further expanded the repertoire for the use of DPP4 inhibitors in the treatment of other metabolic diseases and their consequent complications, which may block the signaling pathway of DPP4 with NFκB and matrix metallopeptidase 9 in these patients." (PMID 33614513, 2021). "MMP-9 and EMMPRIN gene- and protein levels showed similar pattern in non-Mets subjects, which may be indicative of a more regular induction of MMP-9 in patients without this metabolic disorder." (PMID 25191702, 2014).
respiratory diseases (12 papers, 2012 to 2026). "Analyses of cause-specific mortality demonstrated significant associations of MMP-8 and MMP-9 with mortality due to respiratory disease." (PMID 23031278, 2012). "MMP9 polymorphism is identified to increase the susceptibility to respiratory diseases." (PMID 36042908, 2022). "Increasing evidence has revealed the involvement of inflammatory proteins, including cPLA2, COX-2, VCAM-1, ICAM-1, and MMP-9, in the production and development of respiratory diseases." (PMID 40136649, 2025). "In various reports on respiratory diseases, the relationship between NF-κB and MMP-9 has been well demonstrated." (PMID 36678124, 2023). "Among several proteases, MMP-9 is known to have an important part in the progression of respiratory diseases, including COPD." (PMID 36678124, 2023). "Especially MMP-9 and MMP-12 have been associated with elastin degradation and hence with cardiovascular and respiratory diseases." (PMID 22818364, 2012). "Although elastin fragments generated by aggrecanases and cathepsins were identified and may serve as biomarker targets for other indications, our study focused on the activity of MMP-9 and -12 because these proteases are expressed in respiratory diseases." (PMID 22818364, 2012). "Our hypothesis was that elastin degradation by MMP-9 and -12, may provide information to aid diagnosis and progression of respiratory diseases." (PMID 22818364, 2012). "However, little is known about the serum levels of MMP-9 in respiratory diseases." (PMID 38341543, 2024). "Virtual screening and PIN indicated that naringin, chryso-obtusin glucoside, and rubrofusarin-6-O-β-D-gentiobioside were the main active compounds from CGE interacted with MAPK14 and MMP9, which provides the key mechanism of CGE for the treatment of respiratory diseases." (PMID 38974913, 2024).
vasculopathy (12 papers, 2011 to 2025). "Interleukin (IL)-8, IL-6, matrix metalloproteinase (MMP)-2, and MMP-9 levels were elevated in the cerebrospinal fluid of the patients with VZV vasculopathy." (PMID 39062454, 2024). "Markers of fibrosis (TIMP-1 and PIIINP) and vasculopathy (MMP-9) were additionally elevated." (PMID 38956476, 2024). "MMP-9 is a member of MMPs family of at least 26 different zinc (Zn2+)-dependent endopeptidases and plays a necessary role in tissue remodeling, wound healing, inflammation, and vascular disorders." (PMID 33313408, 2020). "Elevated levels of proteases such as MMP-2 and MMP-9 disrupt basement membranes and tight junctions between endothelial cells, potentially contributing to inflammation and vessel wall damage, which are characteristics of VZV vasculopathy." (PMID 39062454, 2024). "We therefore speculate that the upregulation of MMP-9 is a response to SAH specific for the cerebral vasculature, and that the upregulated MMP-9 may play a role in the complex vasculopathy after SAH." (PMID 23259581, 2012). "As inhibition of Notch signaling with Notch1 decoy blocked the induction of MMP9 and MT1-MMP transcripts in HUVEC, blocking Notch signaling in pathological settings may perturb angiogenesis and may prove therapeutically useful in the treatment of vascular disorders." (PMID 21349159, 2011).
colon (9 papers, 2013 to 2025). "It is widely reported that cytokines (IL1β, TNF-α), matrix metalloproteinase (MMP-7, MMP-9) are involved in chronic inflammation, which creates a microenvironment favoring colon carcinogenesis." (PMID 23754197, 2013). "Hereby, in gastrointestinal tumors, infiltrates of neutrophil granulocytes have been observed to produce VEGF, CXCL8, CXCL1, and matrix metalloproteinase-9 (MMP-9)." (PMID 34206809, 2021). "Notably, the expression levels of MMP9 were also strongly upregulated in these tumors, suggesting a key role of the LCN2–SLC22A17–MMP9 network in gastrointestinal tumors." (PMID 36211450, 2022). "Additionally, in gastro-intestinal tumors, endothelial CXCL6 production was evidenced and coincided with leukocyte infiltration and matrix metalloproteinase-9 (MMP-9) expression." (PMID 34503058, 2021).
benign tumors (7 papers, 2003 to 2025). "Moreover, MMP-9 was detected more frequently in malignant breast carcinoma than in benign tumour." (PMID 12698185, 2003).
central nervous system disorder (6 papers, 2020 to 2025). A disease involving the central nervous system. "Recent studies have shown that MMP-9 plays a crucial role in the onset and progression of central nervous system disorders, particularly neuropathic pain." (PMID 41245602, 2025).
inflammatory myopathies (6 papers, 2007 to 2022). "The expression, activation, and regulation of MMP-9 have been linked to inflammatory myopathies." (PMID 36289739, 2022). "In addition, increased expression and activation of MMP-9 are associated with various myopathies and inflammation-induced changes in skeletal muscle." (PMID 28042204, 2016). "Although the exact mechanisms by which excessive production of MMP-9 causes myopathy in mdx mice remain unclear, our analysis showed that the inhibition of MMP-9 increased the protein levels of β-dystroglycan and nNOS and reduced the amounts of active form of TGF-β in myofibers of mdx mice." (PMID 25364719, 2014). "Even though high expression of both IL-17 and MMP-9 has been reported in inflammatory myopathies, the mutual relation of these proteins in muscle is still not well understood." (PMID 28042204, 2016). "In this regard, upregulated MMP-9 in muscle tissue appears to be a common finding in all inflammatory myopathies, while MMP-2 seems to be affected to a lesser extent." (PMID 28042204, 2016). "This notion is further supported by the findings that L-arginine, which improves myopathy in mdx mice, diminishes the expression of inflammatory cytokines and levels of NF-κB and MMP-9 in dystrophic muscle." (PMID 25364719, 2014). "Our published study also provided evidence that although both heterozygous and homozygous deletion of Mmp9 gene attenuates myopathy, the improvement observed in mdx;Mmp9+/− mice is better compared to that of mdx;Mmp9−/− mice." (PMID 23977226, 2013). "We have recently reported that the inhibition of MMP-9 improves myopathy and augments myofiber regeneration in mdx mice (a mouse model of DMD)." (PMID 23977226, 2013). "We have previously reported that heterozygous (i.e. mdx;Mmp9+/−) or homozygous (i.e. mdx;Mmp9−/−) deletion of Mmp9 gene significantly improves myopathy in 8-week old mdx mice." (PMID 23977226, 2013). "In human inflammatory myopathies, it has been reported that MMP-9 is produced primarily by invading T lymphocytes." (PMID 17598883, 2007). "In some inflammatory myopathies, MMP-9 is expressed primarily by invading T lymphocytes, and is implicated in the pathogenesis." (PMID 17598883, 2007). "In addition to high levels of IL-17, elevated levels of MMP-9 have also been observed in skeletal muscle during inflammatory myopathies." (PMID 28042204, 2016). "This suggested that MMP-9/MMP-2 disbalance may be one of the major characteristics of myopathies." (PMID 28042204, 2016). "Furthermore, the formation of new myofibers was increased more dramatically in mdx;Mmp9+/− mice compared to mdx;Mmp9−/− mice indicating that a small amount of MMP-9 may be beneficial whereas excessive amounts of MMP-9 exacerbates myopathy in mdx mice." (PMID 23977226, 2013). "Since IL-17 is primarily a proinflammatory cytokine, this result is in agreement with previous observations that MMP-9 expression is related to the inflammatory response, as well as that MMP-9 upregulation in muscle tissue appears to be a common finding in all inflammatory myopathies." (PMID 28042204, 2016).
neurodevelopmental disorder (5 papers, 2015 to 2023). A behavioral and cognitive disorder with onset during the developmental period that involves impaired or aberrant development of intellectual, motor, or social functions. "Going forward, understanding the precise downstream targets and functions of MMP-9 will be critical for understanding various cellular and molecular mechanisms underlying neurodevelopmental disorders." (PMID 34282726, 2021). "Dysregulated expression and activity of MMP-9 can result in abnormal synaptic remodeling; a hallmark of various neurodevelopmental disorders." (PMID 34282726, 2021). "However, unregulated activity of MMP-9 can have detrimental effects on brain functions and may underlie deficits observed in several neurodevelopmental disorders." (PMID 26283917, 2015). "Our study highlights the importance of MMP-9 in the etiology of neurodevelopmental disorders and future studies will focus on investigating the downstream molecular targets of MMP-9 and the role of other MMPs." (PMID 34282726, 2021). "Such knowledge will guide future clinical studies on the possible role of MMP-9 in neurodevelopmental disorders." (PMID 26283917, 2015). "It is therefore important to better understand the mechanisms by which MMP-9 mediates early postnatal development and its role in neurodevelopmental disorders." (PMID 26283917, 2015). "This review outlines the various actions of MMP-9 during postnatal brain development, critical for future studies exploring novel therapeutic strategies for neurodevelopmental disorders." (PMID 26283917, 2015). "Nonetheless, it is becoming increasingly clear that MMP-9 has multiple functions in CNS development as well, and may contribute to neurodevelopmental disorders." (PMID 26283917, 2015). "It remains to be seen whether PNNs are indeed altered in neurodevelopmental disorders and whether MMP-9 inhibition can recover normal CPP through the stabilization of PNNs." (PMID 26283917, 2015). "Developmental dysregulation of MMP-9 may also lead to neurodevelopmental disorders (ND)." (PMID 34282726, 2021). "In addition, given the overexpression of MMP-9 in multiple neurodevelopmental disorders, it is important to understand whether MMP-9 plays a regulatory and/or permissive role in critical period development, specifically through its interactions with ECM." (PMID 26283917, 2015). "This review summarizes the various roles of MMP-9 in diverse developmental processes within the CNS, with an emphasis on sensory development, and suggests a role for misregulated MMP-9 in neurodevelopmental disorders." (PMID 26283917, 2015).
peripheral neuropathy (5 papers, 2006 to 2024). A disorder affecting the peripheral nervous system. "Research has shown that cisplatin treatment induces peripheral neuropathy, associated with the upregulation of MMP-9 in DRG neurons." (PMID 39664453, 2024). "A proinflammatory protease responsible for the cleavage of MBP to its immunogenic products, matrix metalloproteinase 9 (MMP-9) contributes to acute and late phase peripheral neuropathy." (PMID 31435499, 2019). "Patterns of MMP-9 expression, activity and excretion were assessed in a model of painful peripheral neuropathy, sciatic nerve chronic constriction injury (CCI), in female and male rats." (PMID 29558999, 2018). "In conclusion, the present study offers the first evidence for the excessive, uninhibited proteolytic MMP-9 activity during late-phase painful peripheral neuropathy and suggests that the pattern of MMP-9 expression, activity, and excretion after peripheral nerve injury is universal in both sexes." (PMID 29558999, 2018). "The present study offers the first evidence for the excessive, uninhibited proteolytic MMP-9 activity during late-phase painful peripheral neuropathy and suggests that the pattern of MMP-9 expression, activity, and excretion after peripheral nerve injury is universal in both sexes." (PMID 29558999, 2018). "Our results evidence excessive, uninhibited proteolytic MMP-9 activity in late-phase (day 28) post-CCI and suggest that the roles of MMP-9 in peripheral neuropathy are universal in both sexes." (PMID 29558999, 2018). "Interestingly, MMP-9/2 activity significantly increases in DRG following oxaliplatin treatment, and inhibition of these cytokines can alleviate peripheral neuropathy in mice." (PMID 32843706, 2020). "Thus, the spatial and temporal relation of the specific MMP-9 and TIMP-1 species and binding partners will determine the functional outcomes of their individual and joint activities in painful peripheral neuropathy." (PMID 29558999, 2018). "Exploring MMP9’s role in neuropathic pain and neuronal damage involves understanding its specific mechanisms, across various neuropathic conditions, not just chemotherapy-induced peripheral neuropathy (CIPN)." (PMID 39664453, 2024).
hematological malignancies (4 papers, 2013 to 2025). "Chaudhary with coauthors reported an association between the MMP-9 rs3918242 variant and both environmental factors and addiction habits, suggesting a possible role in the initiation of the progression of hematological malignancies." (PMID 40724896, 2025). "While MMP9 was previously reported to have a critical role in AML invasion and metastasis, the relationship between its expression and the prognosis of hematological malignancies is complicated." (PMID 28298217, 2017). "Considerable evidence has accumulated that MMP9 and MMP2 play an important role in the invasiveness and propagation of several hematological malignancies." (PMID 23289374, 2013).
gastrointestinal disease (3 papers, 2020 to 2025). A disease that occurs in the gastrointestinal system, excluding the hepatobiliary system. "This study highlights that targeting the MMP9/RLN2 signaling axis presents a promising approach to developing new strategies for UC treatment and other related gastrointestinal diseases." (PMID 40529132, 2025).
immune disease (3 papers, 2010 to 2023). "MMP‐9, iNOS, ICAM‐1, and MCP‐1 were demonstrated to participate in the progression of inflammatory and immune disease." (PMID 37904675, 2023).
skeletal dysplasia (3 papers, 2023 to 2025). Any Mendelian diseases that affects growth and development of the skeleton. "Having demonstrated that MMP9 expression is elevated in several in vitro models of COMPopathies, we next asked whether MMP9 expression is altered in a model of another closely related skeletal dysplasia." (PMID 41465495, 2025).
CNS tumors (2 papers, 2017 to 2023). "In summary, we have demonstrated that sEVs’ MMP-9 content is suitable for estimating the probability of patient survival and it allows us to obtain information about CNS tumour aggressiveness." (PMID 36765669, 2023).
genetic disease (2 papers, 2017 to 2022). "We propose that MMP9/MMP13 could be therapeutic targets for patients with this rare genetic disease." (PMID 28158191, 2017).
urinary diseases (2 papers, 2018 to 2019). "Neutrophil gelatinase-associated lipocalin (NGAL), a promising renal biomarker, can exists as a monomer, a dimer and/or in a NGAL/matrix metalloproteinase-9 (MMP-9) complex form when associated with different urinary diseases in humans and dogs." (PMID 31455336, 2019). "Another multiplex panel analysis of proteins in urine samples of BC, healthy controls and other samples with varying urological disorders revealed that urine concentrations of IL-8, MMP-9 and 10, PAI-1, ANG, and APOE were significantly increased in subjects with BC compared to healthy controls." (PMID 30544619, 2018).
blood cancer (1 paper, 2021). "Results from this study so far demonstrate that blood cancer-derived EVs significantly enhance MMP9 and IL-6 secretion from monocytes, which is attenuated by deletion of CypA." (PMID 33984826, 2021). "Similarly, in this study we report that secretion of MMP9 and IL-6 were significantly increased from monocytes upon stimulation with EVs from several blood cancer cell lines." (PMID 33984826, 2021). "To date, the effect of blood cancer EVs on MMP-9 and IL-6 secretion remains unknown." (PMID 33984826, 2021). "CypA-enriched blood cancer EVs were taken up by normal monocytes independent of EV surface trypsin-sensitive proteins and potently stimulated pro-inflammatory MMP9 and IL-6 secretion." (PMID 33984826, 2021).
connective tissue disease (1 paper, 2025). "Concerning early connective tissue disease (CTD)-ILD+ diagnosis, increased MMP-7, MMP-9, MMP-10, and MMP-12 levels were found in RA-ILD+ and SSc-ILD+ patients in relation to RA-ILD- and SSc-ILD- patients, respectively." (PMID 39979794, 2025).
head and neck tumor (1 paper, 2023). "Here, using two head and neck tumor cell lines, SCC-9 and SCC-15, we confirmed increased MMP-9 gene expression in co-culture 3D spheroids compared to mono-culture 3D spheroids on the CAM model using quantitative Taqman PCR." (PMID 36674806, 2023).
muscular disorders (1 paper, 2007). "With respect to muscular disorders, particular attention has been paid to a subgroup of MMPs termed 'gelatinases,' comprising MMP-2 (also called gelatinase A, or 72-kDa type IV collagenase) and MMP-9 (also called gelatinase B, or 92-kDa type V collagenase)." (PMID 17598883, 2007).
musculoskeletal disease (1 paper, 2024). "Some of the prominent MMPs involved in musculoskeletal disease are MMP-1, MMP-3, MMP-9, MMP-13, and MMP-14." (PMID 38790904, 2024).
MMP9 also shares sentences with these, for which no sentence is quoted: acute myocardial infarction (46 papers); chronic periodontitis (30); multiple myeloma (19); hypertrophy (10); essential hypertension (7); primary angle-closure glaucoma (7); colorectal adenoma (6); ascending aortic aneurysm (5); salivary gland cancer (5); benign breast disease (4); dermatitis (4); end stage renal disease (4); hyperthyroidism (4); polycystic ovary syndrome (4); renal failure (4); thyroid (4); Wilms tumor (4); alveolitis (3); anaplastic astrocytoma (3); autism spectrum disorder (3); central obesity (3); chronic apical periodontitis (3); ductal Carcinoma (3); epithelial ovarian tumors (3); Graves’ orbitopathy (3); oral cavity cancer (3); oropharyngeal cancer (3); penile squamous cell carcinoma (3); periapical granuloma (3); peripheral vascular disease (3).
A further 307 diseases each share a sentence with MMP9 in 3 papers or fewer.